STAT3 (signal transducer and activator of transcription 3)
Diseases named in the same sentence as STAT3 in open-access papers (continued):
Sharing a sentence is not in itself a finding about the gene and the disease.
breast cancer (continued). "However, the association between APE1 and STAT3 in the context of breast cancer cell survival and aggressiveness has not been previously characterized." (PMID 41090323, 2025). "Hence, inhibiting the STAT3 signaling pathway may reverse resistance in breast cancer, and offer a novel strategy for managing resistant tumors." (PMID 40949156, 2025). "However, the effect of dual inhibition of APE1 redox activity and STAT3 in breast cancer proliferation, survival, and aggressiveness is still unknown." (PMID 41090323, 2025). "This means that STAT3 may be the key target of BO when treating breast cancer." (PMID 40076902, 2025). "Additionally, BCPO inhibited STAT3 activation in MM, prostate and breast cancer cell lines." (PMID 40333803, 2025). "In breast cancer, exposure to dim nighttime lighting (dLAN) disrupts the circadian rhythm of melatonin, which drives intrinsic resistance to paclitaxel through epigenetic mechanisms, increases STAT3 expression, and enhances breast tumors’ sensitivity to paclitaxel, inhibiting its growth." (PMID 40756978, 2025). "Therefore, we showed for the first time that dual targeting of redox APE1 and STAT3 could decrease the cell invasion of MCF‐7 breast cancer cells." (PMID 41090323, 2025). "Thus, given that both STAT3 and β-catenin are activated in a subset of breast tumors, it was hypothesized that STAT3 may provide a further mechanism by which β-catenin is regulated in breast cancer cells." (PMID 40952540, 2025). "Thus, the current and previous findings that MH inhibits the phosphorylation of STAT3 in breast cancer cells may also play a role in the blockade of tumor progression." (PMID 39064812, 2024). "In addition, epidemiological data have shown that obesity is a risk factor for postmenopausal breast cancer and exacerbates cancer progression, and the upregulation of S1P/S1PR1/STAT3 signaling has also been implicated in a mouse model of breast cancer associated with obesity." (PMID 38542328, 2024). "Moreover, STAT3 upregulates cyclin D1 to regulate cell cycle progression in breast cancer." (PMID 39768178, 2024). "Thus, the research's primary aim is to examine if naringin, alone or in combination with the chemotherapeutic drug doxorubicin, could inhibit the growth and multiplication of MCF-7 breast cancer cells by suppressing the STAT3 signaling pathway." (PMID 38310190, 2024). "This study investigates the potential of Wharton’s Jelly mesenchymal stem cell-derived exosomes (WJ-Exo) as carriers of S3I-201 and their effects on STAT3 expression in breast cancer cell lines, and evaluates whether these exosomes can enhance the anti-tumor effect of S3I-201." (PMID 39294673, 2024). "Moreover, we utilized the JAK2/STAT3-specific inhibitor WP1066 to determine whether activation of this pathway is essential for the CCT2-mediated progression of breast cancer cells." (PMID 39079960, 2024). "However, Stat3 gene targets elevated in the Fyn neurodegeneration model included tnfrsf1a; its human homolog (TNFRSF1A) encodes a receptor for TNF-α (also known as TNF) and is associated with activation of the NF-κB pathway in breast cancer." (PMID 39641161, 2024). "Furthermore, PATZ1 is targeted by miR-29b, a microRNA biomarker for the HER2-enriched subtype, with its expression negatively associated with this subtype, and overexpression of miR-29b inhibits breast cancer cell proliferation and induces apoptosis primarily by downregulating STAT3 protein levels." (PMID 39452108, 2024). "Furthermore, it has been found that WithaD, a chemotherapeutic agent, effectively prevents macrophage M2-polarization by decreasing ERK/STAT3 pathway activation, suppressing breast cancer progression and tumor angiogenesis by eliminating lactate-induced M2 macrophage polarization." (PMID 39003350, 2024). "Treatment with STAT3 inhibitors alone or in combination with other clinical therapeutic drugs may have more promising effects on suppressing or reversing chemoresistance in breast cancer." (PMID 38625901, 2024).
breast cancer (continued). "Their study demonstrated that Luteolin could suppress the EGF-induced activities of EGFR signaling in human breast cancer cell lines and suggested that STAT3, MAPK/ERK1/2, and PI3K/Akt signaling pathways are the main pathways through which Luteolin exhibits its effects on EGFR signaling." (PMID 36992138, 2023). "Therefore, targeting the STAT3 pathway is an attractive strategy for breast cancer treatment." (PMID 37569363, 2023). "TAMs can play a role in endocrine resistance; for example, macrophages may induce endocrine resistance in ER+ breast cancer cells by inducing sustained release of TNF-α and IL-6 from breast cancer cells, resulting in activation of NFκB, STAT3, and ERK-1 and hyperphosphorylation of ERα." (PMID 36909339, 2023). "In addition to STAT5, the other STAT family member activating commonly in breast cancer is STAT3." (PMID 36882838, 2023). "Similarly, changes in p-STAT3 were observed, indicating that the STAT3 signaling pathway may also be involved in the regulation of breast cancer stem cells by Six1." (PMID 38031089, 2023). "STAT3 is a critical transcription factor for maintaining tumorigenesis and tumor initiation via regulating the transcription of genes involved in the preservation of the stem cell phenotype in multiple cancer types such as glioma, prostate cancer, breast cancer, and liver cancer." (PMID 37743465, 2023). "Therefore, further studies are necessary to determine whether TRIM47 upregulation in breast cancer is attributable to genomic amplification or NF-κB/Stat3-mediated transcriptional upregulation." (PMID 36906594, 2023). "In addition, TAMs was reported to regulate murine breast cancer stem cells through a novel paracrine EGFR/Stat3/Sox-2 signalling pathway and promote prostate cancer stem cells self-renewal and prostate cancer metastasis via activating β-catenin/STAT3 signalling." (PMID 38041196, 2023). "The authors also proposed that the expression of ER and phosphorylated STAT3 (pSTAT3) may be considered independent prognostic factors in breast cancer, and that targeting IL-6/STAT3 could have clinical potential in ER-positive, endocrine therapy-refractory patients." (PMID 37834225, 2023). "However, it has also been reported that STAT3 blockade in in vitro murine breast cancer models can induce cellular senescence, and that turning off the constitutive activation of STAT3 in certain cancer cell types may induce senescence." (PMID 36825563, 2023). "Furthermore, WP1066 could reverse the upregulation of PD-L1 processed by MLN8237 by inhibiting p-STAT3 in breast cancer cells." (PMID 37781397, 2023). "Notably, the STAT3 activity can be positively modulated by mTOR in breast cancer stem-like cells." (PMID 38017510, 2023). "Withaferin A is also responsible for the induction of apoptosis in human breast cancer and colon cancer cells by the inhibition of cell invasion and migration by affecting the activation of the signal transducer and activator of transcription 3 (STAT3) transcription activator and ROS generation." (PMID 37259311, 2023). "Notably, we presented evidence for the first time that activated forms of HER2 and HER3 receptor proteins as well as cytoplasmic STAT3 phospho-PTMs forms in breast cancer cells can be directly targeted using our approach, which was referred to as the “TRIM-ing” process." (PMID 38213543, 2023). "Together, these findings indicate that down-regulation of PD-L1 N-linked glycosylation was connected to inhibition of STAT3 and STAT1 activation (noted in MCF-7 cells), and to reduced cell-autonomous and PD-1-induced tumor cell invasion and release of pro-tumorigenic factors in breast cancer cells." (PMID 37830552, 2023).
breast cancer (continued). "Additionally, circRHOT1 could promote the progression of breast cancer by regulating miR-106a-5p/STAT3." (PMID 37924099, 2023). "Therefore, targeting the PDGFRA/STAT3/IL-6 pathway using PDGFRA inhibitors might serve as a therapeutic option to reduce tumor aggressiveness in HER2+ breast cancer." (PMID 36979654, 2023). "Similarly, high expression of STAT3 was found in the nucleus of endometrioid adenocarcinoma, high expression of p-STAT3 was found in the nucleus of hepatocellular carcinoma, and high expression of STAT3 and p-STAT3 was found in the cytoplasm and nucleus of breast cancer." (PMID 36225196, 2022). "In conclusion, our data revealed that paeoniflorin promotes SIRT4 expression to enhance the sensitivity of ER-positive breast cancer cells to tamoxifen by suppressing STAT3 activation, suggesting that paeoniflorin could be used as a drug candidate for the treatment of ER + breast cancer." (PMID 35154350, 2022). "Given that Stat3 activity promotes chemotherapy resistance, and the results that H182 in combination with cisplatin or docetaxel had a synergistic effect against breast cancer cells in vitro, we were interested to determine the antitumor efficacy of combining H182 and radiation therapy." (PMID 35276290, 2022). "The blockade of IL-6 would serve to block the downstream, protumourigenic effects of TAMs, thus supporting the idea that targeting of IL-6R and gp130 may present a better approach to inhibition of this pathway in breast cancers instead of the use of JAK/STAT3 inhibitors." (PMID 35053592, 2022). "In continuation of our research on the effects of inhibition of JAK2/STAT3 signaling pathway in breast cancer tumor cells, the aim of this study was to investigate whether CPT, naringenin, and their combination could modify immune response, immune cell proliferation, and cytokine production." (PMID 35606804, 2022). "Therefore, targeting Angiotensin initiation of NF-kB/IL-6/JAK2/STAT3 pathway could be a beneficial strategy in breast cancer therapies." (PMID 36431925, 2022). "An anti-STAT3 drug may soon be useful in the treatment of breast cancer for TNBC treatment." (PMID 35314590, 2022). "STAT3 and p-STAT3 may, therefore, have multiple functions in breast cancer." (PMID 35314590, 2022). "In addition, it is still unknown whether the effect of the IL-19/IL-20RB/STAT3 axis is specific to lung cancer or also applies to other cancer types, such as breast cancer." (PMID 36006737, 2022). "Moreover, genistein can influence metastasis and induce apoptosis by inhibiting Akt, as well as NF-κB cascades, in PC3 cell lines and MDA-MB-231 breast cancer cell lines, as well as inhibiting the IL-6/STAT3 pathway in MDA-MB-453 breast cancer cell lines, thus inhibiting cell proliferation." (PMID 35956766, 2022). "Moreover, targeting STAT3 in human breast cancer cells was reported to suppress the tumor progression by regulating the expression of crucial proteins in tumor milieu, such as survivin, chemokines (CCL5 and CXCL10) and proinflammatory cytokines (IL-6, IL-5, TNF-a, and IFN-γ)." (PMID 33957948, 2021). "Similarly, 10,11-dehydrocurvularin (DCV), a natural-product macrolide derived from marine fungus, has been shown to selectively suppress the STAT3, to consequently inhibit the proliferation, migration and invasion of breast cancer cells (MDA-MB-231 and MDA-MB-468), via induction of apoptosis." (PMID 33957948, 2021). "As previous study has reported that blocking of STAT3 in breast cancer cells induced an antitumor immune response involving CD4+ T cells, which may ameliorate TME via secretion of cytokines, such as TNF-α, IFN-γ, IL-6, and IL-5, as well as chemokines CCL5 and CXCL10." (PMID 33957948, 2021). "Similarly, RB1 inactivation in breast cancers enhances stem cell-like behaviors and malignant progression through IL-6 and following activation of signal transducer and activator of transcription 3 (STAT3) activation." (PMID 34359636, 2021).
breast cancer (continued). "However, another study found that in breast cancer, IL-17 significantly induced MDSCs differentiation, inhibited their proliferation, and triggered apoptosis via activating Stat3, although low IL-17 inhibited the activation of Stat3, leading to increase formation of MDSCs." (PMID 35003065, 2021). "Therefore, whether EZH2 takes part in the cancer-promoting role of STAT3 in breast cancer remains to be clarified." (PMID 34335938, 2021). "In addition, activation of STAT3 can promote EMT in breast cancer cells." (PMID 33506060, 2021). "In addition, the activation of STAT3 was correlated with poor prognosis in breast cancer patients." (PMID 34833950, 2021). "Thus, CD36-induced activation of the ERK1/2 and STAT3 signalling pathways in the adipocyte environment may account for the enhanced proliferation, migration and invasion of breast cancer cells." (PMID 34561446, 2021). "In addition, HIF1α also plays key roles in promoting CSC phenotypes through ITGA6 forkhead box protein M1 (FOXM1), miR-215, and signal transducer and activator of transcription 3 (STAT3) activation in breast cancer, pancreatic cancer, colon cancer, and glioma, respectively." (PMID 34482364, 2021). "Therefore, elucidating concrete molecular mechanisms modulating the STAT3/Tregs in breast cancer derived TME may prove essential in the development of novel immunotherapy strategies." (PMID 33957948, 2021). "Moreover, STAT3 is a well-identified oncogenic regulator in breast cancer." (PMID 33686957, 2021). "Only a few mice injected with cells expressing Stat3 Y705F developed tumors and these tumors had a lower growth rate, confirming that targeting STAT3 (and phosphorylation of its residues) could be a very effective therapeutic strategy against breast cancer." (PMID 34440160, 2021). "Moreover, IL-6 activated the STAT3 was specifically enriched in co-culture system between macrophages and breast cancer MCF-7 cells as compared to control, which also showed significant upregulation of transforming growth factor β (TGF-β1) and hypoxia-inducible factor-1α (HIF-1α) mRNA levels." (PMID 33957948, 2021). "In the present study, we further demonstrate that 13R,20-diHDHA has potential anti-inflammatory effects and can inhibit breast cancer stemness by inducing ROS production to alter Stat3/IL-6 signaling, and thus may be a promising potential therapeutic agent acting against breast CSCs." (PMID 33804152, 2021). "Moreover, the overexpression of STAT3 and miR-106a-5p inhibitor could reverse circRHOT1 knockdown-mediated breast cancer progression." (PMID 33686957, 2021). "Overall, these data expand our previous findings of an Sdc-1-dependent modulation of a CSC phenotype in breast cancer cells via the IL6/STAT3-, Wnt- and Notch-pathways and suggest that Sdc-1 knockdown may induce differentiation of the CSC population, thus attenuating malignant properties." (PMID 34070901, 2021). "To confirm whether the inhibitory effect of NDRG2 overexpression on PD-L1 expression was related to the regulation of STAT3 or NF-κB activation in mouse breast cancer cells, we examined the phosphorylation levels of STAT3 and NF-κB in 4T1-mock and -NDRG2 cells." (PMID 34885221, 2021). "The activation of STAT3, a major transcription factor, has been confirmed to play an important role in promoting cell growth, migration, invasion, and chemoresistance in many types of malignant tumors, including pancreatic cancer, breast cancer, head and neck cancer, ovarian cancer, and lung cancer." (PMID 33824475, 2021). "In addition, activation of the miR-337-3P/STAT3 axis induced by chronic stress may increase breast cancer metastasis." (PMID 34988010, 2021). "Therefore, STAT3-mediated ROS accretion might play a pivotal role in CD8+ T cell responses of breast cancer than MMPs." (PMID 33957948, 2021).
breast cancer (continued). "Thus, they concluded that MSCs could suppress breast cancer pathogenesis and sensitize cancer cells to radiotherapy through down-regulating the STAT3 pathway, providing a novel therapeutic for breast cancer in terms of overcoming radioresistance." (PMID 34736460, 2021). "Furthermore, we asked whether the STAT3–TrkA interaction can be detected in a triple-negative human breast cancer xenograft." (PMID 34066153, 2021). "Although it has been suggested that STAT3 is the regulator of METTL8 gene expression in mouse embryonic development, it is an important result of showing that METTL8 expression in humans, especially in breast cancer conditions, is caused by not STAT3, but the YY1 transcription factor." (PMID 34063990, 2021). "Moreover, Anxa2 could activate STATS by directly bingding to STAT3, and consequently involve in the invasion and metastasis in breast cancer cells." (PMID 33903672, 2021). "Likewise, compound 3, which contains a dihydroxypropyl 3′-oxime substituent together with an OCH3 group, is a potent inhibitor of Src kinase, and it downregulated the constitutively activated signal transducer and activator of transcription 3 (STAT3) or STAT5 in human breast cancer CML cells." (PMID 34067242, 2021). "Therefore, a rational approach to build upon the STAT3 target immunotherapy strategy such as radiation therapy, which might enhance the systematic antitumor immune responses and therapeutic effects in breast cancers." (PMID 33957948, 2021). "Additionally, STAT3 expression was slightly lower in breast cancer patients." (PMID 34063990, 2021). "Thus, HDGF depletion combined with STAT3 activity inhibition impedes breast cancer radioresistance." (PMID 34376200, 2021). "Moreover, suppressing the STAT3-mediated metabolism may inhibit the breast cancer cellular proliferation." (PMID 34298639, 2021). "Thus, STAT3 and IKKα could integrate, and coordinately mediate the growth and progression of human breast cancer." (PMID 33396715, 2020). "However, some studies report that STAT3 is downstream of HER2 and may be associated with CSCs in this subtype of breast cancer also." (PMID 32391382, 2020). "Previous efforts to identify mechanisms of resistance to CDK4/6 inhibition have found that lack of Rb protein, increased cyclin E expression, IL6/STAT3 pathway activation and decreased DNA repair are some of the underlying mechanisms of resistance in ER+ breast cancer cells." (PMID 32344635, 2020). "Thus, the reduced expression of PD-L1 could be attributed to the poor activation of STAT3 signaling in ObR sh breast cancer clones." (PMID 32727138, 2020). "Importantly, TRPM7 mediated calcium signals further modulate EMT in breast cancer cells, which TRPM7 deficiency specifically reduces EGF-induced STAT3 phosphorylation and the expression of Vimentin, suggesting that TRPM7 is required for maintaining a mesenchymal feature in breast cancer cells." (PMID 32211326, 2020). "In addition, resistin facilitates breast cancer progression via TLR4/nuclear factor kappa-light-chain-enhancer of activated B cells (NF-κB)/signal transducer and activator of transcription 3 (STAT3) signaling pathway-mediated induction of mesenchymal phenotypes and stemness properties." (PMID 33313320, 2020). "Thus, 20(S)-25-OCH3-PPD could potently block IL-6-induced STAT3 activation in breast cancer cells and HepG2 cells, with very low toxicity to normal liver cells." (PMID 32425780, 2020). "In solid tumors, including prostate cancer and breast cancer, STAT3 activation which was mediated by IL-6 could enhance the expression of anti-apoptotic proteins, such as BCL2 or survivin which has constantly been regarded as a protective mechanism from chemotherapy-induced cell death." (PMID 32391256, 2020).